CD109 (CD109 molecule)
Diseases named in the same sentence as CD109 in open-access papers (continued):
Sharing a sentence is not in itself a finding about the gene and the disease.
asthma (3 papers, 2022 to 2025). "In AR, the top 5 significant KEGG pathways associated with CD109 included “intestinal immune network for immunoglobulin A production,” “autoimmune thyroid disease,” “asthma,” “allograft rejection,” and “antigen processing and presentation”." (PMID 41327642, 2025). "Previous studies have shown that blocking CD109 with monoclonal antibodies can inhibit airway inflammation in a house dust mite-induced asthma mouse model." (PMID 41327642, 2025). "CD109 significantly influences inflammation in pulmonary tissues, suggesting that it affects both IPF and asthma." (PMID 39990858, 2024).
brain tumors (3 papers, 2021 to 2025). "The co-expression of HER family members, with EGFRvIII, CD44, and CD109 was examined in the tumour specimens from patients with a brain tumour." (PMID 40227788, 2025). "Following the determination of the expression of HER family members, EGFRvIII, CD44, and CD109 in tumour specimens from patients with a brain tumour, a Fishers Exact correlation test was performed to find any association between the expression of these receptors and the clinicopathological features." (PMID 40227788, 2025). "To date, there are limited studies of CD109 in patients with a brain tumour." (PMID 40227788, 2025). "Moreover, CD109 has been shown to be overexpressed in many neoplasms, including brain tumors, and to promote lung cancer metastasis via the STAT3 activity." (PMID 33986188, 2021). "Also, the most promising biomarkers for the discrimination between LGG plus GT and PA were TMSB4X and CD109, while the most promising biomarkers for the discrimination between EMB MB and all the other brain tumors were 14.3.3 (YWHA-Z,G,E) and HSP90 alpha." (PMID 33469081, 2021).
diffuse large B-cell lymphoma (3 papers, 2018 to 2022). "Additionally, a significant association was observed between high CD109 expression and low 1-year survival in patients with diffuse large B-cell lymphoma." (PMID 29731998, 2018). "CD109 was of interest because increased expression correlates with worse outcome in AML and diffuse large B-cell lymphoma." (PMID 35371997, 2022).
sarcoma (3 papers, 2013 to 2022). A usually aggressive malignant neoplasm of the soft tissue or bone. "CD109 mRNA was highly expressed in various sarcoma cell lines, but weakly expressed in normal adult tissues." (PMID 24376795, 2013). "The expression status suggested that CD109 might be a candidate therapeutic target not only for sarcoma but also for epithelial cancer." (PMID 24376795, 2013). "Moreover, CD109 is a promising prognostic biomarker and a molecular target of cancer therapy for sarcomas including ES." (PMID 24376795, 2013). "In addition to ES, CD109 mRNA expression was observed in 9 of 14 (64%) sarcoma cell lines." (PMID 24376795, 2013). "In other previous studies, some genes (CCND1, CD109, NOS1, and ABLIM1) were found to be abnormally expressed in sarcomas, which can be used as prognostic markers or classification features for different sarcomas." (PMID 36619306, 2022). "The present study also demonstrated that CD109 was highly expressed in sarcoma but not in normal tissues." (PMID 24376795, 2013). "We assessed the CD109 mRNA expression profiles in sarcomas and human fetal and normal adult tissues by RT-PCR." (PMID 24376795, 2013). "Finally, we demonstrate that CD109 is a potential CSC/CIC marker that may be useful as a prognostic biomarker and a molecular target of cancer therapy for sarcomas, including ES." (PMID 24376795, 2013).
adenosquamous carcinoma (2 papers, 2015 to 2018). A carcinoma composed of malignant glandular cells and malignant squamous cells. "Thus, CD109 may be a potential pathology marker for gallbladder squamous cell/adenosquamous carcinomas." (PMID 26249215, 2015). "Similarly, Dong and co-workers showed that CD109 is expressed in bladder squamous cell carcinomas and adenosquamous carcinomas but not in adenocarcinomas or normal gallbladder tissue." (PMID 29731998, 2018).
COVID-19 (2 papers, 2023 to 2025). A disease caused by infection with severe acute respiratory syndrome coronavirus 2. "Polymorphism in human platelet antigen (HPA)-1 and HPA-3 (GPIIb/IIIa), HPA-2 (GPIb/IX), HPA-4 (GPIIIa), HPA-5 (GPIa/IIa), & HPA-15 (CD109) was investigated in 86 COVID-19-infected patients with thrombocytopenia (Group A) and 136 COVID-19-infected patients without thrombocytopenia (Group B)." (PMID 38020117, 2023).
gallbladder cancer (2 papers, 2015 to 2016). "In this study, CD109 protein expression in three subtypes of gallbladder cancer was examined by immunohistochemistry on human tissue samples and tissue microarrays." (PMID 26249215, 2015).
head and neck squamous cell carcinoma (2 papers, 2018 to 2021). A squamous cell carcinoma that arises from any of the following anatomic sites: lip and oral cavity, nasal cavity, paranasal sinuses, pharynx, larynx, and salivary glands. "The serum CD109 levels in a total of 112 serum samples collected before and after surgery from 56 head and neck squamous cell carcinoma patients were analyzed with an enzyme‐linked immunosorbent assay." (PMID 33565282, 2021). "The aim of this study is to evaluate the diagnostic significance of serum CD109 in head and neck squamous cell carcinoma (HNSCC)." (PMID 33565282, 2021). "We also found overexpression of CD109 in other EGFR overexpressing head and neck squamous cell carcinoma cell line HN5." (PMID 29731998, 2018). "CD109 in sera could be a novel prognostic marker for head and neck squamous cell carcinoma involving lymph node metastasis." (PMID 33565282, 2021).
lymph node metastasis (2 papers, 2021). "In our ELISA‐based analysis of HNSCC, a CD109 level above the cut‐off value (preoperative CD109 level of 38.0 ng/ml and CD109 index of 1.6) was associated with a poor prognosis and lymph node metastasis." (PMID 33565282, 2021). "Although further clinical studies of CD109 are required to improve these limitations, CD109 is expected to be a novel prognostic marker or therapeutic target for HNSCC in cases with lymph node metastasis." (PMID 33565282, 2021). "In terms of lymph node metastasis, differential expression of NEGR1, NTNG1, XPNPEP2, CD109, OPCML, and PRND had statistical significance in the groups of N0 and N1." (PMID 34737762, 2021).
myxofibrosarcoma (2 papers, 2018 to 2021). A malignant fibroblastic neoplasm arising from the soft tissue. "Finally, the expression of CD109, a gene previously shown to be a promising diagnostic marker and a potential therapeutic target in myxofibrosarcoma, was 2.19 (p < 0.05) fold-higher than that of the control." (PMID 34768995, 2021). "Furthermore, we investigated CD109 expression in order to provide support to our previous research in which the role of this marker in diagnosis and as a therapeutic target in STS was pointed out, especially in myxofibrosarcoma." (PMID 34768995, 2021).
non-small cell lung carcinoma (2 papers, 2021 to 2024). A group of at least three distinct histological types of lung cancer, including non-small cell squamous cell carcinoma, adenocarcinoma, and large cell carcinoma. "Soluble CD109 has been observed in patient’s serum suffering from non-small cell lung carcinoma and was associated with a poor prognosis." (PMID 33738281, 2021). "In this study, we show that silencing of CD109 in human non-small cell lung cancer (NSCLC) cells, returns these cells to an epithelial like growth phenotype." (PMID 38562713, 2024). "It was shown before that CD109 can be sorted to exosomes and increasing levels of full-length CD109 circulating in patients suffering from non-small cell lung carcinoma." (PMID 33738281, 2021).
oral squamous cell carcinoma (2 papers, 2019 to 2020). "A recent study reported that CD109 expression blocked the TGF-β-elicited EMT process; however, CD109 overexpression was shown to alleviate TGF-β-mediated suppression of cell growth in oral squamous cell carcinoma." (PMID 33375719, 2020).
osteoporosis (2 papers, 2025). A condition of reduced bone mass, with decreased cortical thickness and a decrease in the number and size of the trabeculae of cancellous bone (but normal chemical composition), resulting in increased fracture incidence. "Cd109, a GPI-anchored cell-surface glycoprotein involved in TGFß signaling identified as a causal gene for osteoporosis, also shows increased expression in mutant osteocytes." (PMID 40683889, 2025).
ovarian carcinoma (2 papers, 2023 to 2025). A malignant neoplasm originating from the surface ovarian epithelium. "To determine whether STAT3 and NOTCH1 signaling pathways are implicated in CD109-induced drug resistance in ovarian cancer cells, we examined the effects of STAT3 and NOTCH1 inhibitors on CD109-induced drug resistance." (PMID 37373457, 2023). "A high expression of CD109 correlates with poor prognosis and chemoresistance in patients harboring EOC, but the role of CD109 in the drug resistance of ovarian cancer cells and its underlying mechanism remain largely unknown." (PMID 37373457, 2023). "In this study, we explored the role of CD109 in the drug resistance of ovarian cancer cells in vitro and in vivo." (PMID 37373457, 2023). "Based on previous studies, we compared CD109 expression in the ovarian cancer cell line A2780 and a previously established drug-resistant ovarian cancer cell line (A2780-R)." (PMID 37373457, 2023). "CD109-overexpressed A2780 cells showed an increase in ABCB1 and ABCG2 protein expression levels, which are associated with drug resistance and the poor prognosis of ovarian cancer." (PMID 37373457, 2023). "Therefore, targeted therapy with CD109 will be useful for the treatment of chemotherapy-resistant ovarian cancer." (PMID 37373457, 2023).
psoriasis (2 papers, 2016 to 2024). An autoimmune condition characterized by red, well-delineated plaques with silvery scales that are usually on the extensor surfaces and scalp. "CD109 is also reportedly associated with human psoriasis, and CD109-deficient mice have been shown to exhibit inflammatory cell infiltration of the dermis." (PMID 27756876, 2016). "While CD109's essential role in the epidermis was established through findings from its critical function in psoriasis, it also plays a key role in the dermis." (PMID 39990858, 2024). "Analysis of CD109 expression in psoriasis patients by our group revealed that CD109 protein expression is markedly decreased in psoriatic epidermis as compared to adjacent uninvolved skin." (PMID 39990858, 2024). "CD109 expression is reduced in psoriatic epidermis, while increased release from keratinocytes may drive molecular changes in psoriasis." (PMID 39990858, 2024). "This raises the possibility that CD109 protein release is enhanced in psoriatic keratinocytes and suggest that aberrant CD109 release from the cell surface in human keratinocytes may induce molecular changes that are observed in psoriasis." (PMID 39990858, 2024). "The reduced expression of CD109 leads to diminished TGF-β signaling, leading to psoriasis by allowing increased Smad7 activity and subsequent inflammation." (PMID 39990858, 2024).
urothelial carcinomas of the bladder (2 papers, 2014 to 2016). "We previously reported that CD109 is expressed in urothelial carcinomas of the bladder in an immunohistochemical study." (PMID 24400073, 2014). "We previously reported high levels of CD109 expression in various tumor cell lines and tumor tissues including SCCs of the lung, esophagus, uterus and oral cavity; malignant melanoma of the skin; and urothelial carcinoma of the urinary bladder." (PMID 27756876, 2016).
allergic disease (1 paper, 2024). An immune response that occurs following re-exposure to an innocuous antigen, and that requires the presence of existing antibodies against that antigen. "In addition, CD109 expression is linked to reduced TGF-β signaling in Th2 cells, impacting their differentiation and function in allergic diseases such as chronic rhinosinusitis with nasal polyps." (PMID 39990858, 2024).
astrocytomas (1 paper, 2021). "Kaplan-Meier survival analysis demonstrated that high CD109 expression associated with poorer survival (P = 0.024) of patients with increasingly malignant, diffusively infiltrating astrocytomas (grades II–IV)." (PMID 33986188, 2021). "To study the possible clinical relevance of CD109, we performed immunohistochemical (IHC) analysis of a large cohort of clinical astrocytoma tumor microarray specimens (grades II–IV; n = 346)." (PMID 33986188, 2021).
Autoimmunity (1 paper, 2024). The occurrence of an immune reaction against the organism's own cells or tissues. "By modulating Th1, Th2, and Th17 pathways, CD109 likely help prevent excessive inflammation and autoimmunity, and thus playing a crucial role in maintaining immune balance and reducing the risk of inflammatory diseases." (PMID 39990858, 2024). "CD109 may play a key role in immune balance by preventing excessive inflammation and autoimmunity via its regulation of T helper cells (Th1, Th2, and Th17 pathways)." (PMID 39990858, 2024).
brain cancer (1 paper, 2025). A primary or metastatic malignant neoplasm affecting the brain. "The association between the expression level of HER-family members, EGFRvIII, CD44, and CD109, and the overall survival of Brain cancer patients." (PMID 40227788, 2025).
breast tumors (1 paper, 2025). "CD109, AHNAK2, and MFGE8 in breast BRCA1-mut cancers, and B3GNT7, CTSV, and GSDMC in BRCA2-mut breast tumors." (PMID 40647506, 2025).
cervix (1 paper, 2020). "Moreover, CD109 protein expression was enhanced at the cell membrane of a subset of cervical tumour cells." (PMID 32507856, 2020).
emphysema (1 paper, 2023). "Regarding the upregulated DEGs in COPD, CD109, B cell linker (BLNK), interleukin-1 receptor type 1 (IL1R1), CD1A, and carboxypeptidase A3 (CPA3) are related to T-helper cell type 2 (Th2) inflammation, but not to emphysema formation." (PMID 38203236, 2023).
endometriosis (1 paper, 2025). The growth of functional endometrial tissue in anatomic sites outside the uterine body. "Meanwhile, our study suggested that higher levels of EPHB4, RSPO3, FSHB, and SEZ6L2 were associated with an increased risk of endometriosis, while lower levels of CD109, SAA1, and SAA2 were also associated with an increased risk of endometriosis." (PMID 40450304, 2025). "In this study, we found that low expression of CD109 may be associated with an increased risk of endometriosis." (PMID 40450304, 2025). "Therefore, CD109 may help prevent excessive inflammation and autoimmunity, playing a key role in maintaining immune balance and reducing the risk of inflammatory diseases.The inflammatory nature of endometriosis has been well established over the years." (PMID 40450304, 2025). "CD109, SAA1, SAA2, FSHB, and SEZ6L2 are weakly associated with endometriosis, with higher levels of FSHB and SEZ6L2 correlating with an increased risk of endometriosis, and higher levels of CD109, SAA1, and SAA2 correlating with a decreased risk of endometriosis (PFDR < 0.05, PPH4 < 0.6)." (PMID 40450304, 2025). "We found that the druggable genes EPHB4, CD109, SAA1, SAA2, FSHB, and SEZ6L2 may be associated with the pathogenesis of endometriosis and are potential therapeutic targets for drug treatment." (PMID 40450304, 2025). "This study indicates that the druggable genes EPHB4, CD109, SAA1, SAA2, FSHB, and SEZ6L2 may be associated with the pathogenesis of endometriosis and are potential therapeutic targets for drug treatment." (PMID 40450304, 2025). "Therefore, we speculate that CD109 may be involved in the pathogenesis of endometriosis by regulating the inflammatory response." (PMID 40450304, 2025). "CD109, SAA1, SAA2, FSHB, and SEZ6L2 are considered to provide low-level evidence of colocalization with endometriosis (PPH4 ≤ 0.6)." (PMID 40450304, 2025).
fibrosis (1 paper, 2026). the formation of excess fibrous connective tissue in an organ or tissue in a reparative or reactive process. "The current study investigates the impact of CD109 knockout (KO) on skin fibrosis using a bleomycin-induced fibrosis mouse model." (PMID 41898693, 2026).
head and neck cancer (1 paper, 2021). A primary or metastatic malignant neoplasm affecting the head and neck. "At the chromosome level, the amplification of a specific region associated with the overexpression of CD109 has been confirmed in head and neck cancer cell lines." (PMID 33565282, 2021).
heart failure (1 paper, 2018). Inability of the heart to pump blood at an adequate rate to meet tissue metabolic requirements. "CD109 did not appear in the list of proteins associated with heart failure generated by random forest regression." (PMID 30557359, 2018).
idiopathic pulmonary fibrosis (1 paper, 2024). Idiopathic pulmonary fibrosis (IPF) is a nonneoplastic pulmonary disease that is characterized by the formation of scar tissue within the lungs in the absence of any known cause. "Idiopathic pulmonary fibrosis (IPF) is one of the pulmonary diseases in which CD109 expression is dysregulated." (PMID 39990858, 2024).
invasive carcinoma (1 paper, 2014). A carcinoma that is not confined to the epithelium, and has spread to the surrounding stroma. "Variable CD109 protein expression was observed in the invasive carcinoma cells, ranging from weak, moderate, to strong staining." (PMID 25635161, 2014).
liposarcoma (1 paper, 2013). A usually painless malignant tumor that arises from adipose tissue. "Positive CD109 expression, including in well-differentiated liposarcomas, was significantly associated with decreased probabilities of overall survival (OS) and disease-free survival (DFS) (P=8.3×10-5 and 4.5×10-4, respectively)." (PMID 24376795, 2013). "Moreover, excluding well-differentiated liposarcomas, positive CD109 expression was also significantly associated with decreased probabilities of OS and DFS (P=0.006 and 0.049, respectively)." (PMID 24376795, 2013).
liver cirrhosis (1 paper, 2016). "Other characteristics, including sex, HBsAg, AFP, liver cirrhosis, tumor number, and tumor encapsulation, were not related to CD109 expression on tumor vessels." (PMID 27121053, 2016).
malignant glioma (1 paper, 2021). A grade III or grade IV glioma arising from the central nervous system. "CD109 associates with STAT3 phosphorylation and poor survival of malignant gliomas." (PMID 33986188, 2021).
malignant ovarian teratoma (1 paper, 2022). "A potential autosomal recessive variant of CD109 was discovered in a patient with malignant ovarian teratoma, with an increase in minor allele frequency compared to the control population." (PMID 35774118, 2022).
nasal polyps (1 paper, 2024). "In nasal polyps, a distinct subset of Th2 cells expressing CD109 was identified." (PMID 39990858, 2024).
osteoarthritis (1 paper, 2020). A noninflammatory degenerative joint disease occurring chiefly in older persons, characterized by degeneration of the articular cartilage, hypertrophy of bone at the margins and changes in the synovial membrane. "Inhibitors of WNT (DKK3 and FRZB), and antagonists of BMP/TGFβ (CD109, CHRDL2, DCN FMOD, INHBA and THBS1) signalling were decreased or absent in the aged inner region, consistent with the reported upregulation of these pathways in IDD and its closely related condition osteoarthritis." (PMID 33382035, 2020).
Osteopenia (1 paper, 2022). Osteopenia is a term to define bone density that is not normal but also not as low as osteoporosis. "CD109 was also associated with mature OBs, and PTPN11 KO mice exhibited osteopenia phenotypes." (PMID 36181557, 2022).